FUT8 (fucosyltransferase 8)
Diseases named in the same sentence as FUT8 in open-access papers (continued):
Sharing a sentence is not in itself a finding about the gene and the disease.
melanoma (22 papers, 2018 to 2025). A malignant, usually aggressive tumor composed of atypical, neoplastic melanocytes. "α1,6-fucosyltransferase, encoded by FUT8, has demonstrated involvement in biological and tumour characteristics and is upregulated in various cancers including lung, liver, colorectal, ovarian, prostate, breast, melanoma, thyroid, and pancreatic." (PMID 33466384, 2021). "A systems biology approach recently identified core fucosylation as a crucial factor in the aggressive behaviour of melanoma cells and showed FUT8 is a key driver of melanoma metastasis." (PMID 40387385, 2025). "FUT8‐mediated core fucosylation also plays an important role in cancer biology, and upregulation of FUT8 has been identified in numerous cancer types including lung, liver, colorectal, thyroid, melanoma, pancreatic, ovarian, breast and prostate cancer." (PMID 40387385, 2025). "To predict the prognosis of melanoma patients, we calculated the risk score of each patient based on the expression and corresponding lambda value of seven genes (PLA2G2D, FUT8, PLA2G4E, PLA2G5, PLA2G1B, B3GNT2, and ST3GAL5)." (PMID 37205993, 2023). "Because core fucose plays important roles in the development of COPD and melanoma metastasis, the regulation of FUT8 expression or activity is important for improving the pathology of these diseases." (PMID 36336076, 2022). "has identified Fut8 as the core fucosyltransferase to fucosylate PD-1 and positively regulates cell-surface PD-1 expression, thus inhibition of Fut8 reduces PD-1 cell-surface expression and promotes T-cell antitumor activity in melanoma." (PMID 34631531, 2021). "The increase in FUT8 expression in melanoma cells was found to be transcriptionally regulated by TGFβ-induced factor homeobox 2 (TGIF2)." (PMID 34440905, 2021). "In melanoma, up regulation of FUT8 was identified as a driving factor of metastasis via reducing cleavage of fucosylated adhesion molecule, L1CAM." (PMID 34703796, 2021). "Agrawal and colleagues performed a systematic analysis of the melanoma glycome of clinical samples and found upregulation of core fucosylation (FUT8) and downregulation of α-1,2 fucosylation (FUT1, FUT2) as features of metastatic melanoma." (PMID 34440905, 2021). "FUT8 has been reported as a driver of melanoma metastasis and silencing of FUT8-suppressed invasion and tumor dissemination." (PMID 31022917, 2019). "FUT8 is a driver of melanoma metastasis, which when FUT8 silenced, suppresses cell invasion and tumor dissemination were suppressed." (PMID 30619732, 2018). "In melanoma, the core-fucosylation (α-1,6 fucosylation) mediated by fucosyltransferase 8 (FUT8) was reported to promote melanoma progression, while branched fucosylation through the α-1,2 linkage inhibits melanoma progression." (PMID 29924834, 2018). "Unlike prior studies that linked FUT8 mediated glycosylation to melanoma metastasis, our work demonstrates a causal role for MGAT4B in tumor initiation." (PMID 40424122, 2025). "Interestingly, L1CAM, which is a FUT8 target and mediator of cancer progression in melanoma, showed downregulation in this case, suggesting an alternate mechanism in RCCs." (PMID 38703764, 2024). "FUT8-knockdown alone significantly reduced melanoma cell migration, an effect that was only partially rescued by the simultaneous overexpression of FUT4, suggesting that while both FUTs impact melanoma motility, their functional contributions are not redundant." (PMID 38326303, 2024). "Indeed, FUT8 silencing decreased cell invasion and in vivo melanoma metastasis, suppressing the ability of melanoma cells to colonize distant organs." (PMID 34440905, 2021). "The ability of uncleaved L1CAM to interact with the vasculature at distal organs may explain how FUT8 contributes to melanoma metastases." (PMID 34440905, 2021).
melanoma (continued). "Indeed, the core-fucosylation (α-1,6 fucosylation) mediated by FUT8 promotes melanoma progression, whereas branched fucosylation through the α-1,2 linkage inhibits melanoma invasion and progression." (PMID 34440905, 2021). "Here, we summarise the role of FUT8 in various cancers (including lung, liver, colorectal, ovarian, prostate, breast, melanoma, thyroid, and pancreatic), discuss the potential mechanisms involved, and outline opportunities to exploit FUT8 as a critical factor in cancer therapeutics in the future." (PMID 33466384, 2021). "In melanoma, TGIF2 directly upregulates the transcription of FUT8 (fucosyltransferase 8) to induce metastasis, increasing the aggressive nature of the cancer." (PMID 34965271, 2021). "For example, FUT8-mediated core fucosylation alters L1CAM proteolytic cleavage, which facilitates melanoma cell invasion and tumor dissemination." (PMID 33976130, 2021). "Several studies have reported that the silencing of FUT8 in cultured prostate, melanoma, lung, breast, and HCC cancer cells that express high levels of FUT8 inhibits invasion, migration, proliferation, colony formation, tumor growth, and metastasis." (PMID 31450600, 2019).
prostate carcinoma (20 papers, 2016 to 2025). A carcinoma that arises from epithelial cells of the prostate gland. "The findings presented above suggested overexpression of FUT8 is linked to high grade prostate cancer and can promote an aggressive cell phenotype." (PMID 40387385, 2025). "FUT8 has previously been identified as upregulated in prostate cancer tumours and linked with the development of high‐grade disease." (PMID 40387385, 2025). "Mechanistically we show FUT8 regulates the expression of genes and signalling pathways linked to prostate cancer progression." (PMID 40387385, 2025). "The expression level of FUT8 holds potential as a biomarker possessing either prognostic or diagnostic significance in many cancers including prostate cancer, pancreatic cancer, gastric cancer, and colorectal cancer." (PMID 38277230, 2024). "High expression of FUT8 and haptoglobin was observed in prostate cancer cell lines, and serum levels of fucosylated haptoglobin were associated with high-grade prostate cancer." (PMID 34948129, 2021). "In contrast the abundance of proteins associated with cell motility and prostate cancer metastasis increased when FUT8 expression is elevated." (PMID 33466384, 2021). "FUT8 drives increased core fucosylation in prostate cancer and has been linked to disease progression." (PMID 33466384, 2021). "Overexpression of FUT8 has been recently linked with aggressive and castrate-resistant prostate cancer, as well as being associated with a poor prognosis for patients." (PMID 34359624, 2021). "FUT8 expression increases in aggressive and castrate-resistant prostate cancer, and is linked to poor prognosis in patients (these studies were based on cell lines, and a small number of tissue samples and will need repeating in additional larger cohorts)." (PMID 30893936, 2019). "Overexpression of FUT8 in prostate cancer cells reduces the number of extracellular vesicles secreted by prostate cancer cells and increases the abundance of proteins associated with cell motility and prostate cancer metastasis." (PMID 34948129, 2021). "Together, this data indicates that upregulation of the fucosyltransferase FUT8 underpins the biosynthesis of malignant core fucosylated N‐glycans in prostate cancer cells." (PMID 40387385, 2025). "Mechanistically, we show FUT8 regulates malignant core fucosylated N‐glycans on prostate cancer cells and is correlated with the expression of oncogenic proteins and pathways linked to disease progression." (PMID 40387385, 2025). "FUT8 protein levels were 2.1‐fold higher in men with prostate cancer compared to men with benign disease (n = 319, p < 0.05)." (PMID 40387385, 2025). "Here, we demonstrate using multiple independent clinical cohorts that FUT8 is upregulated in high grade and metastatic prostate tumours, and in the blood of prostate cancer patients with aggressive disease." (PMID 40387385, 2025). "Moving forward, we anticipate these specific FUT8 inhibitors will be relevant for prostate cancer therapy and are candidates for further investigation." (PMID 40387385, 2025). "To test if altered FUT8 expression changes the cell surface core fucosylation of prostate cancer cells, we utilised cell lines with knockdown or overexpression of FUT8." (PMID 40387385, 2025). "Our study cements FUT8‐mediated core fucosylation as an important driver of prostate cancer progression and suggests targeting FUT8 activity for prostate cancer therapy as an exciting area to explore." (PMID 40387385, 2025). "We also detected higher levels of FUT8 protein in serum samples from men with high grade prostate cancer (Gleason grade 8–9) compared to low grade disease (Gleason grade 6–7) (n = 200, p < 0.0218)." (PMID 40387385, 2025). "Our findings show FUT8 underpins the synthesis of malignant core fucosylated N‐glycans in prostate cancer cells and functionally links FUT8 with prostate tumour growth and the regulation of genes and pathways implicated in disease progression." (PMID 40387385, 2025).
prostate carcinoma (continued). "To address this, we created prostate cancer cells with stable overexpression (upregulation) or knockdown (downregulation) of FUT8 and used these to study the effects of FUT8 on prostate cancer cell behaviour." (PMID 40387385, 2025). "Real‐time quantitative PCR detected upregulation of the FUT8 gene in prostate cancer relative to benign prostate hyperplasia (BPH) gland (n = 12, p < 0.01) which was further validated in a larger independent patient cohort (n = 49, p < 0.01)." (PMID 40387385, 2025). "While FUT8 is recognised as a crucial factor in cancer progression, its role in prostate cancer remains poorly understood." (PMID 40387385, 2025). "Next, to test if FUT8 is also upregulated at the protein level in high grade prostate tumours, we used immunohistochemistry (IHC) to monitor FUT8 protein levels in two previously published prostate cancer tissue microarrays (TMAs)." (PMID 40387385, 2025). "Here we monitor FUT8 levels in > 1500 clinical samples across multiple patient cohorts and verify that FUT8 is upregulated in high grade and metastatic prostate tumours and in the blood of prostate cancer patients with aggressive prostate disease." (PMID 40387385, 2025). "Our study identifies FUT8‐mediated core fucosylation as an important player in aggressive prostate cancer and highlights the targeting of FUT8 activity as a promising new strategy for prostate cancer therapy." (PMID 40387385, 2025). "Using pre‐validated sandwich ELISA assays, we monitored FUT8 protein levels in blood samples from men with prostate cancer." (PMID 40387385, 2025). "Moving forward, we propose that both global fucosylation and small molecule inhibitors of FUT8 are relevant to patients with prostate cancer and should be explored as new therapeutic avenues." (PMID 40387385, 2025). "Given the critical roles of FUT8 in prostate cancer biology, it is poised to be a druggable target for cancer therapy." (PMID 40387385, 2025). "Based on these findings, we propose FUT8‐mediated core fucosylation regulates pro‐oncogenic mechanisms involved in prostate cancer progression and this can likely be exploited for therapeutic usage." (PMID 40387385, 2025). "Overexpression of FUT8 in prostate cancer cell lines was also shown to reduce EV release, but it did not affect vesicle size." (PMID 39598633, 2024). "Overexpression of FUT8 has been positively correlated with the epithelial compartment and high grade prostate cancer." (PMID 33466384, 2021). "In particular, higher FUT8 expression is present in high grade prostate cancer compared to low grade prostate cancer." (PMID 33466384, 2021). "They found that increased cellular expression of FUT8 can reduce the number of vesicles secreted by prostate cancer cells and simultaneously enhance the protein abundance correlated with cell motility and prostate cancer metastasis." (PMID 34359624, 2021). "Over expression of FUT8 was also found to be correlated with increased fucosylation of glycoproteins in aggressive prostate cancer cells." (PMID 34703796, 2021). "It was shown that androgen ablation is essential for FUT8 overexpression in AR-positive prostate cancer cells." (PMID 33466384, 2021). "In 2018, the first study was published reporting the functional role of the FUT8 enzyme in castrate-resistant prostate cancer development." (PMID 33466384, 2021). "The findings revealed that the number of vesicles secreted by prostate cancer cells was reduced when the cellular expression of FUT8 was increased." (PMID 33466384, 2021). "We have previously shown that castration or androgen ablation in prostate cancer cells induced overexpression of FUT8." (PMID 32085441, 2020). "In our in vitro data, we have demonstrated that overexpression of FUT8 was regulating the expression of EGFR in prostate cancer cells, which was responsible for the androgen-resistant mechanism." (PMID 32085441, 2020).
prostate carcinoma (continued). "In this study, we evaluated the role of FUT8, a glycosylated related enzyme as a master regulator to be involved in the transformation of prostate cancer cells from nuclear receptor AR-dependent signaling to the cell surface including the EGFR signaling." (PMID 32085441, 2020). "Taken together, our findings suggest a crucial role played by FUT8 as a mediator in switching prostate cancer cells from nuclear receptor signaling (androgen receptor) to the cell surface receptor (EGFR) mechanisms in escaping castration-induced cell death." (PMID 32085441, 2020). "Using prostate cancer models, we have shown that overexpression of FUT8 was sufficient to transform the androgen-dependent LAPC4 prostate cancer cells into androgen-resistant cells." (PMID 32085441, 2020). "In this study, we tried to understand how FUT8 overexpression regulates castration-resistant mechanisms in prostate cancer cells." (PMID 32085441, 2020). "Altered expression of the fucosyltransferases FUT6 and FUT8 are important in advanced prostate cancer." (PMID 30893936, 2019). "Our findings revealed that FUT8 overexpression was in fact driven by androgen ablation in prostate cancer cells." (PMID 29339807, 2018). "Together, these data suggest a positive role of FUT8 in the castration resistance biology of prostate cancer." (PMID 29339807, 2018). "Protein lysates from PC3 cells, an androgen-resistant prostate cancer cell line that had previously shown to express higher levels of FUT8, were included as a positive control for FUT8 expression." (PMID 29339807, 2018). "We thus hypothesised that the FUT8 enzyme might also be detectable in serum/plasma samples from men with prostate cancer." (PMID 40387385, 2025). "Our study provides proof‐of principle data to show metabolic inhibitors of fucosylation can be used to target FUT8‐mediated core fucosylation to reduce prostate cancer cell growth and highlights the potential to utilise these type of inhibitors as new therapies for prostate cancer." (PMID 40387385, 2025). "Future studies could investigate how upregulation of FUT8 in aggressive prostate cancer impacts both bone metastasis and the tumour immune microenvironment (including regulation of osteoblasts and immune checkpoint molecules)." (PMID 40387385, 2025). "Furthermore, FUT8 is yet to be investigated as a potentially important clinical target in prostate cancer." (PMID 40387385, 2025). "Further deciphering the biological effects mediated by FUT8 in prostate cancer could lead to new strategies targeting the FUT8 immune checkpoint axis to improving anti‐tumour immune responses in patients with cancer." (PMID 40387385, 2025). "Furthermore, we find that fucosylation inhibitors can inhibit the activity of FUT8 in prostate cancer to suppress the growth of prostate tumours." (PMID 40387385, 2025). "In additional cohorts of patients with prostate cancer, FUT8 mRNA was upregulated in prostate cancers with a ‘metastatic’ signature compared to tumours with ‘non‐metastatic’ biology (n20, p < 0.05) and in metastatic prostate tumours compared to localised disease (n = 20, p < 0.05)." (PMID 40387385, 2025). "While the full repertoire of specific N‐glycoproteins modified by FUT8 in prostate cancer are likely still to be fully discovered, it is clear the role of FUT8 is multi‐faceted (and likely involves the regulation of cell signalling receptors, cytokines and immune checkpoint molecules)." (PMID 40387385, 2025). "Furthermore, in vitro assays showed that FUT8 can promote prostate cancer cell migration and invasion." (PMID 40387385, 2025). "Additionally, upregulation of FUT8 is correlated with increased fucosylation of glycoproteins in aggressive prostate cancer cells." (PMID 33466384, 2021). "FUT8 was overexpressed in androgen-resistant LAPC4 cells compared with androgen-dependent LAPC4 cells, suggesting the functional role of fucosylated enzymes associated with aggressive prostate cancer." (PMID 34948129, 2021).